SYNJ2 (synaptojanin 2)
Description:
Phosphatase that hydrolyzes phosphate groups from the inositol ring of phosphoinositides and inositol phosphates, in a domain-specific manner. The 5-PPase domain catalyzes removal of the 5-phosphate from substrates such as phosphatidylinositol-4,5-bisphosphate (PtdIns(4,5)P2), phosphatidylinositol-3,4,5-trisphosphate (PtdIns(3,4,5)P3), inositol-1,4,5-trisphosphate (Ins(1,4,5)P3) and inositol-1,3,4,5-tetrakisphosphate (Ins(1,3,4,5)P4). The SAC domain hydrolyzes phosphates at the 3- and 4-positions of the inositol ring, targeting phosphatidylinositol-3-phosphate (PI(3)P), phosphatidylinositol-4-phosphate (PI(4)P), and phosphatidylinositol-3,5-bisphosphate (PI(3,5)P2) (By similarity). Plays a role in the phosphatidylinositol metabolic process during the early stage of clathrin-coated-pit formation. During EGF activation, plays a role in receptor-mediated endocytosis (RME) by converting PtdIns(4,5)P2 to PtdIns(4)P through the H2O2-dependent oxidation of the 4-phosphatase domain (By similarity). May play a role in tumor cell invadopodia formation.
Synonyms: INPP5H
Tractability: Small molecule: a high-quality ligand is known. Antibody: UniProt places it where antibodies can reach, with high confidence; its Gene Ontology location is reachable by antibodies, with medium confidence. PROTAC: ubiquitination databases record sites on it; a small molecule that binds it is known.
Target class: Enzyme; Hydrolase
Gene: Protein-coding gene on chromosome 6 (157,981,863 to 158,099,176, forward strand). Ensembl gene ENSG00000078269.
Subcellular location: Cytoplasm; Cell membrane; Cell projection, ruffle membrane; Presynapse; Cytoplasm, cytoskeleton
Subcellular location (Human Protein Atlas): Microtubules; Cytosol
Pathways (Reactome):
Metabolism: Synthesis of PIPs at the plasma membrane
Vesicle-mediated transport: Clathrin-mediated endocytosis
Gene Ontology:
Molecular function: phosphatidylinositol-3,4,5-trisphosphate 5-phosphatase activity; phosphatidylinositol-4,5-bisphosphate 5-phosphatase activity; protein binding; inositol-1,4,5-trisphosphate 5-phosphatase activity; phosphatidylinositol phosphate 4-phosphatase activity; phosphatidylinositol-3,5-bisphosphate 3-phosphatase activity; phosphatidylinositol-3,5-bisphosphate 5-phosphatase activity; phosphatidylinositol-3-phosphate phosphatase activity; phosphatidylinositol-4-phosphate phosphatase activity; inositol-1,3,4,5-tetrakisphosphate 5-phosphatase activity; nucleic acid binding; phosphatase activity; RNA binding
Biological process: clathrin coat assembly; phosphatidylinositol metabolic process; synaptic vesicle endocytosis; membrane organization; phosphatidylinositol biosynthetic process; receptor-mediated endocytosis; phosphatidylinositol dephosphorylation; phosphatidylinositol-3-phosphate biosynthetic process
Cellular component: cytoplasm; membrane raft; plasma membrane; ruffle membrane; cytosol; membrane; perinuclear region of cytoplasm; presynapse; cytoskeleton
Genetic constraint (gnomAD): Loss-of-function variants: 107 observed, 129.77 expected, observed/expected ratio (o/e) 0.82, 90% interval 0.7 to 0.97. The upper end of that interval is the gene's LOEUF score, 0.97, which puts it in group 4 of 6, group 1 being the genes least tolerant of losing a copy. Missense variants: 1,749 observed, 1,864.9 expected, observed/expected ratio (o/e) 0.94, 90% interval 0.9 to 0.98. Synonymous variants: 709 observed, 748.86 expected, observed/expected ratio (o/e) 0.95, 90% interval 0.89 to 1.01.
Homologues: Orthologues: chimpanzee SYNJ2 (99% identical), macaque SYNJ2 (95% identical), guinea pig SYNJ2 (86% identical), rat Synj2 (84% identical), dog SYNJ2 (84% identical), mouse Synj2 (83% identical), rabbit SYNJ2 (80% identical), pig SYNJ2 (80% identical), tropical clawed frog synj2 (61% identical), Drosophila melanogaster Synj (35% identical), Caenorhabditis elegans unc-26 (29% identical), Drosophila melanogaster CG9784 (8% identical), and 3 more. Paralogues in human: SYNJ1 (41% identical), INPP5D (14% identical), INPP5B (14% identical), INPPL1 (14% identical), OCRL (14% identical), INPP5J (12% identical), INPP5F (10% identical), INPP5E (9% identical), FIG4 (9% identical), INPP5K (7% identical), SACM1L (6% identical), SH2D1B (2% identical), and 1 more.